KCNH2 (potassium voltage-gated channel subfamily H member 2)
Diseases named in the same sentence as KCNH2 in open-access papers (continued):
Sharing a sentence is not in itself a finding about the gene and the disease.
short QT syndrome (42 papers, 2008 to 2026). "Inherited mutations in the KCNH2 gene, which encodes the cardiac hERG potassium channel, are major contributors to arrhythmogenic syndromes such as long QT and short QT syndromes." (PMID 41443252, 2026). "The approach has also been extended to hiPSC-CM models of LQTS type 2 (KCNH2 mutations), short QT syndrome type 1, and calmodulin-associated LQTS, demonstrating its versatility across multiple genotypes and channelopathies." (PMID 40843724, 2025). "Genome editing has been performed to correct the missense mutation T618I in the potassium channel gene KCNH2 in short QT syndrome patience-specific hiPSC-CMs to elucidate the single-cell phenotype of short QT syndrome." (PMID 36895064, 2023). "Well-described genetic variants in KCNH2 have been found to either cause the congenital form or predispose for the acquired form of long QT and short QT syndromes." (PMID 36421807, 2022). "Mutations in KCNH2 cause long or short QT syndromes (LQTS or SQTS) predisposing to life‐threatening arrhythmias." (PMID 34841674, 2021). "There are a number of insights from human-induced pluripotent stem cell models of the short QT syndrome (SQTS) derived from an individual with SQTS type-1 with the N588K mutation in the KCNH2 gene." (PMID 33224525, 2020). "Short QT syndrome type 1 (SQT1) results from gain-of-function mutations in the Kv11.1 (hERG) channel encoded by the KCNH2 gene, and is the best studied SQT subtype with respect to pharmacological treatment." (PMID 28711067, 2017). "The genetic screening in the first two reported families with Short QT Syndrome and sudden cardiac death, led to the identification of two different missense mutations on KCNH2 that resulted in the same amino acid change of the cardiac Ikr channel." (PMID 20126594, 2010). "However, among three definite LQTS genes, KCNQ1 and KCNH2 are also reported as causative genes for the short-QT syndrome." (PMID 36480497, 2022). "The T618I KCNH2-encoded hERG mutation is the most frequently observed mutation in genotyped cases of the congenital short QT syndrome (SQTS), a cardiac condition associated with ventricular fibrillation and sudden death." (PMID 35114584, 2022). "A young patient with short QT syndrome had 2 heterozygous variations in KCNH2 p.(Ala1116Val) and p.(Lys897Thr), which were classified as VUS and benign, respectively." (PMID 39940965, 2025). "Nevertheless, the remainder of this review will principally focus on links between KCNH2/hERG, KCNQ1 and KCNJ2 and short QT syndrome as these potassium channel genes can be causally linked to SQTS with a high degree of confidence." (PMID 37122211, 2023). "The other patient was a female with multiple arrhythmias, in whom a reported stop-gain variant (c.1096C > T, p.R366X) in KCNH2 related to long QT syndrome 2 [MIM:613688] and short QT syndrome 1 [MIM:609620] was identified." (PMID 31382961, 2019). "So far, gain-of-function mutations in KCNQ1, KCNH2, and KCNJ2 have been associated only with rare cases of short QT syndrome (SQTS) and/or AF." (PMID 24972929, 2014). "Loss-of-function KCNH2 mutations are responsible for the LQT2 form of heritable long QT syndrome, whilst gain-of-function mutations are responsible for the SQT1 form of heritable Short QT syndrome (SQTS)." (PMID 23300672, 2012). "Similarly, the SupRep technique was able to substantially increase the shortened APD of hiPSC-CMs carrying the N558K (p.Asn558Lys) gain-of-function mutation in KCNH2 associated with short QT syndrome type 1, although not to the control level, as in our simulations of the SQT3 mutations." (PMID 39769116, 2024).
epilepsy (30 papers, 2015 to 2026). A brain disorder characterized by episodes of abnormally increased neuronal discharge resulting in transient episodes of sensory or motor neurological dysfunction, or psychic dysfunction. "Subject C, a 44-year-old man with recurrent syncope misdiagnosed as epilepsy and a strong family history of sudden death, was found to carry a KCNH2 p.Val612Met variant and had a QTc of 600 ms." (PMID 41768584, 2026). "Mutations in ion channel genes such as SCN5A, KCNA1, and KCNH2 can manifest in both epilepsy and cardiac arrhythmia, illustrating the potential for a shared genetic basis for epilepsy and cardiac diseases." (PMID 40079478, 2025). "Post-mortem genetic analysis indicates a higher prevalence of LOF (3-fold) and rare (11-fold) KCNH2 variants in Sudden Unexpected Death in Epilepsy (SUDEP) cases vs. living epilepsy controls." (PMID 40234944, 2025). "One individual had a frameshifting, pathogenic variant in the KCNH2 gene, which is found in both the Epilepsy and CMAR1 panels." (PMID 38229148, 2024). "There was a higher prevalence of loss-of-function (3-fold) and rare variant (11-fold) KCNH2 variants in SUDEP cases vs. epilepsy controls." (PMID 35600076, 2022). "The results were compared to KCNH2 variants identified in a control sample comprising epilepsy patients who were over 50 years of age." (PMID 34002542, 2021). "Patients with cardiac gene mutations have increased rates of neurological disorders: high rates of epilepsy in patients with LQT2 syndrome due to KCNH2 mutations and high rates of neurodevelopmental delay in patients with CPVT due to RYR2 mutations." (PMID 34930847, 2021). "In our epilepsy control population of 332 living patients with epilepsy over 50 years of age with whole‐exome sequencing data, variants in KCNH2 that satisfied the filtering criteria were found in 20 out of 332 subjects." (PMID 34002542, 2021). "The SUDEP cohort has approximately threefold enrichment for loss‐of‐function KCNH2 variants (OR = 2.7, 95% confidence interval (1.1, 7.4), Fisher’s exact test nominal p = 0.04) compared with the epilepsy control population." (PMID 34002542, 2021). "KCNH2 variants were found in 11.1% (10/90) of SUDEP individuals compared to 6.0% (20/332) of epilepsy controls (p = 0.11)." (PMID 34002542, 2021). "We show an approximate threefold enrichment in loss‐of‐function KCNH2 variants in our SUDEP cohort relative to an older epilepsy control cohort that has “escaped” SUDEP." (PMID 34002542, 2021). "KCNH2 variants were found in 11.1% of SUDEP cases (10/90) compared to 6.0% of epilepsy controls (20/332; p = 0.11)." (PMID 34002542, 2021). "The Arg 744* variant of KCNH2 has previously been reported in people with epilepsy or LQTS." (PMID 40729245, 2025). "Mutation of KCNH2 would result in epilepsy, indicating its role in neuronal electrophysiology." (PMID 36066699, 2022). "In conclusion, our data provide evidence that both rare and more common KCNH2 variants that cause loss‐of‐function may act as biomarkers of SUDEP in epilepsy patients." (PMID 34002542, 2021). "An enrichment of loss‐of‐function KCNH2 variants in SUDEP compared to epilepsy controls argue that cardiac mechanisms may contribute to risk." (PMID 34002542, 2021). "In contrast, blocking of KCNH2 potassium channels can lead to opposite effects, which is supported by the finding that mutations of KCNH2 channels are a potential common background of epilepsy and arrhythmias related to long QT-2 syndrome." (PMID 33492655, 2021). "This hypothesis predicts that SUDEP individuals will have an enrichment of KCNH2 variants that impact channel function compared to epilepsy patients at low risk of SUDEP." (PMID 34002542, 2021). "Genes such as SCN5A, KCNQ1, KCNH2, RYR2 are associated with both channelopathies and epilepsy and almost 40% of people with LQT2 and 20% of those with LQT1 present an epileptic phenotype." (PMID 41062843, 2026).
epilepsy (continued). "The objective of this study is to generate and characterize a genetic rabbit model of Kcnh2-mediated epilepsy, ECG abnormalities, and sudden death (SCD & SUDEP), which reproduces the neuro-cardiac electrical abnormalities seen in people with LQT2." (PMID 40234944, 2025). "Specifically, when compared to an epilepsy control population of 50 years or older (i.e. those who are thought to have “escaped” SUDEP), the prevalence of LOF KCNH2 variants was significantly higher in the SUDEP cohort." (PMID 40234944, 2025). "Similar to our previous study that showed that 18% of people with LQT2 have a history of seizures/epilepsy, 19% of Kcnh2(+/7bp−del) rabbits develop spontaneous epileptiform activity and seizures." (PMID 40234944, 2025). "There is an unmet need for a clinically relevant model of LQT2 to investigate the mechanisms for the high risk of seizures and SUDEP in LQT2 and KCNH2-mediated epilepsy." (PMID 40234944, 2025). "The surprisingly high incidence of epilepsy and seizure in the context of LQT2-associated KCNH2 variants highlights the ability of ERG1 channels to modulate neuronal behavior." (PMID 35600076, 2022). "Loss‐of‐function KCNH2 variants, defined as causing >20% reduction in maximal amplitude, were observed in 8.9% (8/90) SUDEP patients compared to 3.3% (11/332) epilepsy controls suggesting about threefold enrichment (nominal p = 0.04)." (PMID 34002542, 2021). "Patients with a prior epilepsy diagnosis constituted 5 of 19 for LQTS probands (3 KCNH2 and 1 KCNQ1), 2 of 15 for CPVT probands (1 RYR2), and 1 of 15 for BS probands (1 SCN5A)." (PMID 32298319, 2020). "The most prevalent types of LQTS are caused by mutations in three cardiac channels: KCNQ1, KCNH2 and SCN5A, which have been also associated with epilepsy and sudden unexpected death in epilepsy (SUDEP)." (PMID 33375447, 2020). "Interestingly, variants in the KCNH2 gene, which encodes ERG1, another member of the ERG family, have been reported in epilepsy patients, and predominantly located in the PAS domain and pore-forming domain." (PMID 39634124, 2025). "The genes associated with LQTS, KCNQ1, KCNH2, and SCN5A, are common causes of epilepsy." (PMID 40729245, 2025). "KCNH2 variants found in SUDEP and epilepsy control populations." (PMID 34002542, 2021). "There was no enrichment of KCNH2 variants that did not change channel function in the SUDEP cohort compared to the epilepsy control cohort (OR = 0.8, 95% confidence interval 0.17 to 3.8, Fisher’s exact p > 0.99)." (PMID 34002542, 2021). "It would also be informative to identify a cohort with KCNH2 variants of similar functional deficits but without epilepsy to directly assess the impact of the combination of seizures plus arrhythmic predisposition on the risk of death." (PMID 34002542, 2021). "This novel knock-in rabbit model of Kcnh2-mediated LQT2, epilepsy, and sudden death facilitates comprehensive studies to uncover the mechanisms underlying SCD and SUDEP in a population with both neuronal and cardiac electrical abnormalities." (PMID 40234944, 2025). "KCNH2 variants that did not change channel function occurred at a similar frequency in SUDEP (2.2%; 2/90) and epilepsy control (2.7%; 9/332) cohorts (p > 0.99)." (PMID 34002542, 2021).
epilepsy (continued). "Diagnosis of LQTS type 2 (LQT2) was confirmed by ECG and the detection of potassium voltage-gated channel subfamily H member 2 gene (KCNH2) mutation and epilepsy was ruled out and all AEDs were withdrawn based on her normal 24-h video electroencephalograph (VEEG) monitoring." (PMID 34481479, 2021).
channelopathies (27 papers, 2012 to 2026). "ECG abnormalities were reported in 29 subjects (3%); six of those (0.6%) were potentially significant, including one case of genetically confirmed channelopathy (LQT syndrome) caused by a novel KCNH2 pathogenic mutation." (PMID 41300586, 2025). "One of the cases analyzed (ADN001) was previously reported by our group in a study of channelopathies, which described the coexistence of mutations in KCNH2, AKAP9, and the TTN p.Arg34653Cys variant, now reevaluated in this study." (PMID 41465321, 2025). "This aspect is in line with the relative severity of the phenotype related to KCNH2 channelopathies." (PMID 39595626, 2024). "Our gene-based meta-analyses identified a burden of rare coding variants associated with QT, JT, and QRS, in genes typically linked with inherited channelopathies (KCNQ1, KCNH2) and cardiomyopathies (MYH7, TNNI3K)." (PMID 36050321, 2022). "Three cases (34, 286 and 290) had one variant in a cardiomyopathy gene and one in a channelopathy gene (CSRP3 and TRPM4, PKP2 and ANK2, MYH7 and KCNH2, respectively)." (PMID 30615648, 2019). "Indeed, it is recognized that common gene variations (minor allele frequency >0.5% to 20%) in disease-causing channelopathy genes such as KCNH2 and SCN5A may provoke functional alterations in vitro similar to putative mutations in those same genes and yet not lead to an associated phenotype." (PMID 29959160, 2018). "The channelopathies are associated with the following genes: SCN5A, KCNQ1, KCNH2, KCNE1, RYR2." (PMID 38793126, 2024). "Indeed, it is usually performed in cases of research projects, performing the analysis of the most prevalent genes associated with channelopathies (such as KCNQ1, KCNH2, SCN5A, and others), excluding other important candidate genes." (PMID 34356248, 2021). "Regarding the etiology of channelopathies such as the Congenital Long QT Syndromes itself, 75% of LQTS cases are linked to mutations in genes encoding for voltage-gated potassium channel subunits (KCNQ1, KCNH2, KCNE1, KCNE2), or for voltage-gated sodium channel SCN5A." (PMID 36421220, 2022). "Proof-of-concept studies in LQTS models, particularly for KCNH2 (LQT2), have demonstrated that antisense oligonucleotides can modulate splicing and increase functional channel expression, drawing on lessons from cystic fibrosis and other channelopathies." (PMID 40649020, 2025). "When the autopsy does not show any structuralcardiac anomaly, channelopathies he following panel of genes: SCN5A, KCNQ1, KCNH2, KCNE1, and RYR2 should be used." (PMID 38793126, 2024).
breast cancer (22 papers, 2015 to 2026). A primary or metastatic malignant neoplasm involving the breast. "To further explore the role of hERG channel in breast cancer prognosis, we utilized bioinformatic tools to investigate the survival rates of patients with high and low KCNH2 expression." (PMID 39917621, 2025). "Although we believe that it is still premature to withdraw a definitive conclusion about the possible role of KCNH2 in oncogenesis, we believe that these data suggest that the KCNH2 gene presents tumor suppressor characteristics at the least in breast cancer." (PMID 29423049, 2018). "Finally, in the Cancer Genome Atlas KCNH2 was found to be overexpressed in ductal (top 13%), lobular (top 26%) and invasive (top 30%) breast carcinomas." (PMID 29423049, 2018). "Furthermore, in Perou’s study KCNH2 was upregulated in both lobular (top 7%) and ductal (top 16%) breast carcinomas." (PMID 29423049, 2018). "This hypothesis is supported by previous reports showing that the KCNH2 promoter can be found hypermethylated in a variety of cancers, including breast carcinomas, suggesting that in these cancers suppression of Kv11.1 expression might contribute to a hyperproliferative phenotype." (PMID 29423049, 2018). "Initially, we analyzed the expression of the hERG gene (KCNH2) across an array of cancer types and observed a significant correlation with breast cancer." (PMID 39917621, 2025). "Moreover, we found six sex-biased genes (EGFR, CDK6, PRKCB, PDCD1, KCNH2, FCGR3B, and TOP2A) in BRCA were the therapeutic targets of breast cancer." (PMID 39175079, 2024). "Activation of Kcnh2 using activator NS1643, however, improved survival rate of breast cancer through a mechanism whereby inhibiting cell motility, attenuating Wnt/β‐catenin signalling to reprogramme epithelial–mesenchymal transition and suppressing cancer cell stemness." (PMID 33263944, 2021). "Our bioinformatics investigation indicates that KCNH2 gene presents a differential expression profile independent of breast cancer histological subtypes, but there is a higher degree of expression in the metastatic phenotype." (PMID 29423049, 2018).
congenital long QT syndrome (22 papers, 2013 to 2024). "In Long QT Syndrome 2, mutations in KCNH2 (aka human ether-a-go-go related gene/HERG) encoding the rapidly activating-delayed rectifier potassium channel Kv11.1 alpha-subunit alter cell repolarization of the ventricular action potential." (PMID 26664897, 2015). "Moreover, cells with mutations in HERG/KCNH2 channels that cause long QT syndrome 2 have prolonged action potential durations and other electrical abnormalities that may affect maturation processes." (PMID 25688759, 2014). "Susceptibility to congenital long QT syndrome (LQTS) is mediated by rare and common variation at 15 genes including KCNQ1, KCNH2, and SCN5A6,7." (PMID 36050321, 2022). "Second, some patients with familial long QT syndrome suffer from genetic KCNH2 abnormalities." (PMID 24887423, 2014). "Clinical genetic testing of the individuals with phenotypic QT prolongation for variants in congenital long QT syndrome (cLQTS) related genes revealed a variant of unknown significance in KCNH2 p.R164H (Clinvar, VCV000067508.8) that did not segregate with the disease phenotype." (PMID 39070617, 2024).
Brugada syndrome (19 papers, 2014 to 2025). "Variants in KCNQ1 (NM_000218.2) or KCNH2 (NM_000238.3) responsible for Romano-Ward long-QT syndrome types 1, 2, and 3 and for Brugada syndrome, were observed in 4 individuals." (PMID 32231684, 2020). "So far, such risk stratification has been applied to SCN5A, KCNQ1, and KCNH2 gene variants associated with Brugada syndrome and long QT syndrome types 1 and 2, respectively, but risk stratification of HCN4 gene variants related to sick sinus syndrome has not yet been performed." (PMID 37760888, 2023).
colorectal cancer (19 papers, 2005 to 2025). A primary or metastatic malignant neoplasm that affects the colon or rectum. "Knockdown of hERG1 (KCNH2) expression led to reversion of the EMT profile in colorectal cancer cell lines, leading to reacquisition of the epithelial-like profile." (PMID 35326596, 2022). "The human ether a gò-gò related (hERG1) channels (KCNH2 or Kv 11.1, according to the most recent nomenclature) are voltage-dependent K+ channels that are overexpressed in human endometrial adenocarcinoma, myeloid leukaemia and colorectal cancer." (PMID 16175187, 2005).